GPRC5A (G protein-coupled receptor class C group 5 member A)
Diseases named in the same sentence as GPRC5A in open-access papers (continued):
Sharing a sentence is not in itself a finding about the gene and the disease.
tumor (continued). "The function of GPRC5A in cancers may need to be discussed under specific context of tumor." (PMID 33753999, 2021). "Furthermore, GPRC5A can be induced by hypoxia, regulates the NF-κB-mediated expression of Vanin-1 (a key enzyme of cysteamine generation), and influences the reactive oxygen levels contributing to tumor progression." (PMID 30417009, 2018). "However, one early study suggested that GPRC5A exhibits a tumor-suppressive role in EGFR-expressing MDA-MB-231 cells and that GPRC5A knockdown promotes colony formation, cell growth, cell migration and invasion capacities in this cell line, but has no such effect in EGFR-negative MCF7 cells." (PMID 30417009, 2018). "Therefore, the proliferation of different tumour cells may respond to GPRC5A expression differently." (PMID 27273304, 2016). "Thus, we proposed that the tyrosine-phosphorylated GPRC5A could be used as a prognostic marker for tumor progression." (PMID 25311788, 2014). "Tumor-specific deep crypt secretory cells (tDCS, cluster 10) demonstrated elevated expression of TFF1, FABP1, CKB, PRAP1, IL32, GPRC5A, and SOD3, and were consistent with secretory lineage plasticity and immune or stress-associated signaling." (PMID 41282138, 2025). "To further confirm that KACs give rise to tumour cells, we labelled KRT8+ cells in Gprc5a−/−;Krt8-creER;RosatdT/+ mice." (PMID 38418883, 2024). "PTGES level was significantly higher in tumors than those in adjacent normal tissues, whereas GPRC5A and CD8+ expression were higher in adjacent normal than tumor tissues." (PMID 32060421, 2020). "To extend this analysis further, we further examined, by IHC staining assay, GPRC5A and PTGES in 50 pairs of lung tissues from normal and tumor tissues." (PMID 32060421, 2020). "For example, CPPED1, GPRC5A, and TAGLN, recently reported to have tumor-suppressive function (57, –, 59), were significantly downregulated at both the mRNA and protein level." (PMID 30918060, 2019). "In vivo studies showed that knockdown of hsa_circ_006100 delayed tumour growth, reduced PCNA expression and upregulated miR‐195 and BCL‐2 expression which was restored by miR‐195 inhibition due to GPRC5A/EGFR signalling, and changed the EMT phenotype in vivo." (PMID 31318114, 2019). "Furthermore, targeting GPRC5A may also provide a new means to inhibit tumour‐specific YAP activity." (PMID 30143543, 2018). "GPRC5A is a member of orphan class C of the GPCR superfamily and was originally identified as a tumor suppressor playing an important role in lung tumor development." (PMID 30417009, 2018). "Moreover, since hypoxia frequently occurs in the therapy‐resistant regions of tumours where the utility of hypoxia‐targeted drugs is limited, the development of inhibitors to GPRC5A may lead to novel cancer‐selective drugs that could serve as adjuncts to conventional chemo‐ and radiotherapy." (PMID 30143543, 2018). "GPRC5A was localized in the plasma membrane and intracellular vesicles, and no cellar localization difference was found between normal HOK and tumor HN30 cells." (PMID 28270740, 2017). "Gprc5a-/- mice exposed to NNK alone developed multiple lung tumors, while NTHi exposure increased the number of hyperplastic foci 6-fold and the tumor multiplicity 2-fold." (PMID 22239913, 2012). "Compared to control Gprc5a-KO mice, NNK-treated mice developed lung tumors at least 6 months earlier, exhibited 2- to 4-fold increased tumor incidence and multiplicity, and showed a dramatic increase in lesion size." (PMID 20686609, 2010). "Correspondingly, GPRC5A and YAP1 had similar expression patterns in tumor tissues." (PMID 36735162, 2023). "MiR-135b-5p and GPRC5A were conspicuously decreased in the tumor tissue of miR-135b-5p antagomir+Ad-NC group, and the expression of KLF4 was higher than NC group, while GPRC5A level in the miR-135b-5p antagomir+Ad-GPRC5A group was markedly higher than that in the other 2 groups." (PMID 35027543, 2022).
tumor (continued). "We further illustrated that the Sca-1+/Abcg1+ subset isolated from Gprc5a-KO mice that had not yet developed tumors showed self-renewal and tumor initiation capabilities." (PMID 32157214, 2020). "We further isolated Sca-1+Abcg1+ cells from Gprc5a−/− mouse lungs that had not developed tumors and proved the capacities of these cells for self-renewal and tumor initiation." (PMID 32157214, 2020). "It is thus plausible that expression programs we underscored in the Gprc5a−/−Kras-mutant LUAD CSCs may be conserved, at least in part, in human KRAS-mutant LUAD; particularly programs influencing stemness, pro-tumor inflammation and antioxidant function." (PMID 31001473, 2019). "Conversely, we found that Wnt7a, a component of the Wnt/β-catenin pathway and the loss of which was previously reported to promote an undifferentiated tumor-protective phenotype in NSCLC, was markedly suppressed in the Gprc5a−/−Kras-mutant LUAD CSCs relative to parental cells." (PMID 31001473, 2019). "Tumor growth of MDA-F471 parental cells and dissociated G1 spheres was evaluated by subcutaneous injection of various cell numbers (500,000, 10,000, and 1,000 cells) into 11 or 12 Gprc5a−/− mice per group (and per cell number)." (PMID 31001473, 2019). "GPRC5A in samples of non‐small cell lung carcinoma (NSCLC) tissue was expressed at lower levels than in corresponding adjacent normal tissues and functioned as a tumour suppressor." (PMID 31318114, 2019). "Compared to GPRC5A wild-type cells, GPRC5A knockout cells have higher levels of activated-STAT3 and STAT3-regulated anti-apoptotic genes, independent of the presence of exogenous epidermal growth factor (EGF), resulting in enhancement of tumor progression." (PMID 30417009, 2018). "The phosphorylation of GPRC5A in two conserved double-tyrosine (TYR) motifs, TYR-317/TYR-320, and TYR-347/TYR-350 is mediated by epidermal growth factor receptor (EGFR), leading to inactivation of the protein's tumor suppressive function." (PMID 30417009, 2018). "Importantly, overexpression of ectopic GPRC5A in HNSCC cells inhibits IL-6-induced STAT3 activation and suppresses the anchorage-independent tumor growth." (PMID 28270740, 2017). "Interestingly, the expression levels of GPRC5A and p-STAT3 were inversely correlated, even in different area from the same tumor tissue." (PMID 28270740, 2017). "We found that GPRC5A repression was significantly correlated with tumor grade in HNSCC tissues (P < 0.01), but was not correlated with other parameters such as gender, TNM stage, alcohol or tobacco consumption." (PMID 28270740, 2017). "We found that generally in both normal pancreatic tissue and adjacent normal pancreatic tissue from tumor, there was low to medium expression of GPRC5A protein in pancreatic ductal cells; however, in primary PDAC samples, GPRC5A protein levels increased dramatically." (PMID 27415424, 2016). "IHC analysis with specific antibody to Y317/Y320-P site showed that GPRC5A in NSCLC tissues is mostly phosphorylated, whereas GPRC5A in adjacent tumor tissues is mostly non-phosphorylated." (PMID 25311788, 2014). "Histological examination revealed that the lungs of untreated Gprc5a -/- mice contained almost no tumor or hyperplastic lesion at the age of one year." (PMID 22239913, 2012). "Taken together, these results suggest that, PGE2 from tumor cells can induce polarization of M2 macrophages in vitro; and PTGES/PGE2 signaling-upregulated TAMs and myeloid cells are strongly correlated with immunosuppression and lung metastasis in Gprc5a-ko mouse lungs." (PMID 32060421, 2020).
tumor (continued). "Thus, small and confined nodules suggests that wild-type mouse lungs had the ability to confine or restrain the pathological effects of silica particles, whereas Gprc5a−/− mouse lungs failed to do so, leading to formation of neoplasia." (PMID 26447616, 2015). "Conversely, proteins hypophosphorylated (Tumor/Normal phosphorylation spectral count ratio >1) in tumors include the transcription factors STAT1 and STAT5, the protein tyrosine phosphatase PTPN11, the G-protein coupled receptor GPRC5A, and the kinases MAPK1, MAPK3, and TNK2." (PMID 19946374, 2009). "However, human lung tumour cells are heterogeneous and the proliferation status in different tumour cells may be affected by more complicated factors/pathways and are not solely affected by GPRC5A or EGFR." (PMID 27273304, 2016). "However, while these data show an in vivo association between GPRC5A, hypoxia gene signatures and patient outcomes, it is important to note that this may be a reflection of GPRC5A's regulation by HIF activity/hypoxia in aggressive tumours, rather than necessarily indicating a functional role." (PMID 30143543, 2018).
cancer (63 papers, 2009 to 2026). A tumor composed of atypical neoplastic, often pleomorphic cells that invade other tissues. "Based on the fact that GPRC5A is less studied and lacks its specific association with cancer, we chose MLLT11 for a deeper study." (PMID 38075552, 2023). "This association of GPRC5a with metastatic potential corroborates with this gene being an emerging biomarker of human cancer." (PMID 36007057, 2022). "In HGSC patient tumors, this orphan receptor GPRC5A was expressed exclusively in cancer cells and associated with chemotherapy resistance and poor survival." (PMID 32115889, 2020). "It encodes for an orphan G-protein coupled receptor GPRC5A differently expressed in several human cancer entities." (PMID 32719397, 2020). "What is more, GPRC5A deficiency reduces cell proliferation and promotes cell apoptosis in vitro and inhibits tumorigenesis of a colitis-associated cancer model in vivo." (PMID 30417009, 2018). "This review aimed to summarize our updated view on the biology and regulation of GPRC5A, its expression in human cancers, and the linked signaling pathways." (PMID 30417009, 2018). "Another in vitro study demonstrated the interaction of miR-103 with GPRC5A, a G-protein-coupled receptor that has been associated with a variety of cancers." (PMID 26057471, 2015). "Previous microarray analysis showed that the transcriptomes of lung epithelial cells of GPRC5A-knockout defined a loss-of-GPRC5A gene signature, which was characterized by many aberrations in cancer-associated pathways, and was prevalent in human LUACs compared with SQCCs or normal lung." (PMID 36781501, 2023). "GPRC5A is associated with various cancer initiation and progression." (PMID 33788883, 2021). "Therefore, the results of different studies are controversial and no meta‐analysis has been performed to assess the diagnostic utility of GPRC5A among multiple types of cancer." (PMID 33788883, 2021). "In recent years, the GPRC5A gene has received special attention due to its implication in various types of cancer, including lung, breast, colorectal, and prostate cancer." (PMID 40427604, 2025). "Aberrant GPRC5A expression was correlated with overall survival, disease-specific survival, and progression-free interval in specific cancers." (PMID 39006081, 2024). "Remarkably, among 675 human cancer cell lines, the mRNA expression of GPRC5A in PC cell lines exhibited the highest level." (PMID 38634049, 2024). "Based on cancer stages, compared with the normal group, we found that patients in higher stages had more GPRC5A expression." (PMID 36735162, 2023). "It is meaningful to explore the structure of GPRC5A and determine agonists or inhibitors to investigate its effectiveness in clinical trials for cancer treatment." (PMID 36735162, 2023). "Previous research has shown that GPRC5A promotes cancer cell adaptation to hypoxia by activating YAP1, the core protein of the Hippo pathway." (PMID 36735162, 2023). "GPRC5A can have the role of tumor suppressor or of oncogene depending on the different cancer types, adding more complexity to the unraveling of its cellular signaling and molecular mechanisms." (PMID 35399533, 2022). "GPRC5A expression is induced by hypoxia in a cancer cell line, subsequently activating YAP/TAZ to promote survival of the cells in hypoxic conditions." (PMID 36310237, 2022). "Apart from Cdkn1c, other cancer-related genes, such as RASSF7 and GPRC5A has also been linked with Klf5 in this study." (PMID 33923166, 2021). "Collectively, these data highlight FMN2 and GPRC5A as targets for cellular vulnerabilities of cancer cells." (PMID 33708620, 2021). "The potential comprehensive roles of this protein in several aspects of cancer development, plus its frequent overexpression in PDAC, make GPRC5A a potentially promising therapeutic and diagnostic target." (PMID 34522225, 2021). "Further studies for this mechanism will be necessary to reveal novel insights into application of GPRC5A in cancers." (PMID 33788883, 2021).
cancer (continued). "In this study, we conducted a systematic review and meta-analysis to examine the prognostic value of GPRC5A in different types of human cancers from a collection of published results." (PMID 33788883, 2021). "According to the literature selection procedure, 624 studies related to GPRC5A and cancer prognosis were identified from online database searches using specific search terms." (PMID 33788883, 2021). "Functional analysis of GPRC5A confirmed that GPRC5A promoted hypoxic cancer cells survival via the Hippo pathway effector YAP." (PMID 33708620, 2021). "The expression of GPRC5A differed in various human cancers, indicating its dual role in tumorigenesis." (PMID 33753999, 2021). "Further studies focused on the cellular and molecular mechanisms will be necessary to reveal novel insights into application of GPRC5A in cancers." (PMID 33788883, 2021). "In response, this meta‐analysis was conducted to examine the prognostic value of GPRC5A in different types of human cancers from a collection of published results." (PMID 33788883, 2021). "Actually, the gene has been reported to play critical roles in embryonic development and epithelial cell differentiation, the dysregulation of GPRC5A was known to be involved in multiple cancers including lung, breast, colon and other types of cancers." (PMID 34819098, 2021). "By immunoblotting of patient‐derived cells, EphA2 (total and phosphorylated), GPRC5A, and RSK showed variable expression in the cancer cells, whereas GPRC5A was undetectable and RSK low in patient‐derived CAFs." (PMID 32115889, 2020). "Altogether, these results reinforce the link between cancer cell‐expressed GPRC5A, the RSK1/2‐EphA2 signaling inhibition, and treatment sensitivity of HGSC cells." (PMID 32115889, 2020). "We intended to analyze the connection between Rho GTPases, GPRC5A expression and proliferation in breast epithelial and cancer cells." (PMID 32719397, 2020). "GPRC5A was first identified in 1998 in numerous types of human cancer, including colon cancer, colorectal cancer, and pancreatic cancer." (PMID 33680947, 2020). "First and foremost, we demonstrated up-regulation of markers in CSCs from Gprc5a−/−Kras-mutant LUAD that are widely known to be overexpressed in stem cells of different cancers." (PMID 31001473, 2019). "For example, Greenhough and co-authors recently identified that HIFs are activators of GPRC5A transcription (G Protein-coupled Receptor Class C, Group 5, Member A), a new mediator of cancer cell survival during hypoxia." (PMID 31487965, 2019). "Here, we used SILAC‐based proteomics to identify the orphan G protein‐coupled receptor GPRC5A as a novel hypoxia‐induced protein that functions to protect cancer cells from apoptosis during oxygen deprivation." (PMID 30143543, 2018). "Accumulating studies have demonstrated GPRC5A dysregulation in various human cancers, although its expression status differs among different cancer types." (PMID 30417009, 2018). "By analysing the entirety of proteins whose levels are changed following cancer cell growth in low oxygen, we identified elevated expression of a G protein‐coupled receptor, called GPRC5A." (PMID 30143543, 2018). "GPRC5A (G protein-coupled receptor class C group 5 member A) encodes retinoic acid-induced protein 3 (RAI3), which is associated with many types of cancers." (PMID 30214686, 2018). "Compared to control PDEC cells, GPRC5A had the greatest fold-increase (>eightfold) in expression in all four PDAC cell samples with larger fold-increases in the primary cancer cells, 34E and 79E." (PMID 29872392, 2018). "Although GPRC5A is predominately expressed in normal lung tissues, dysregulation of GPRC5A expression has been observed in a variety of human cancers." (PMID 30417009, 2018). "Our study showed that GPRC5A was highly expressed in normal tissues, but it was down-regulated in precancerous lesion, and greatly suppressed in malignant tumors." (PMID 28270740, 2017).